MIR1202 (microRNA 1202)
Synonyms: hsa-mir-1202; MIRN1202
Gene: MicroRNA gene on chromosome 6 (155,946,797 to 155,946,879, forward strand). Ensembl gene ENSG00000221456.
Homologues: Orthologues: chimpanzee ptr-mir-1202 (100% identical).